HLA-DRB1 (major histocompatibility complex, class II, DR beta 1)
Diseases named in the same sentence as HLA-DRB1 in open-access papers (continued):
Sharing a sentence is not in itself a finding about the gene and the disease.
T-LGL leukemia (2 papers, 2022 to 2023). "Patients with concurrent T-LGL leukemia and RA are also enriched in HLA-DRB1*04 alleles associated with RA." (PMID 35646651, 2022). "Although additional studies are needed to precisely compare the immunogenetic similarities between T-LGL leukemia and RA, the enrichment of RA-associated HLA-DRB1*04 alleles in patients with T-LGL leukemia who develop RA suggests the presence of a shared immunogenetic scaffold." (PMID 35646651, 2022). "Past reports have also observed a high prevalence of HLA-DRB1*04 alleles in both diseases (86.7% in FS; 82.8% in LGL leukemia/RA patients; 31.4% in LGL leukemia patients, which is similar to control population rates) as well as response to methotrexate therapy in both diseases." (PMID 35646651, 2022).
upper respiratory tract infection (2 papers, 2009 to 2025). "The liver damage observed in the current patient, associated with the upper respiratory tract infection, could be linked to the HLA-DRB1 04:01 genotype." (PMID 40079016, 2025). "For example, future research could explore the role of Class II diversity, especially HLA-DRB1, in susceptibility to common infectious diseases such as upper-respiratory tract infections." (PMID 19633717, 2009).
visceral leishmaniasis (2 papers, 2022 to 2023). A severe form of leishmaniasis characterized by irregular bouts of fever, substantial weight loss, swelling of the spleen and liver, and anemia (which may be serious). "This study suggests that the r-LdODC protein, as well as its derived HLA-DRB1-restricted synthetic peptides, have immunoprophylactic potential and can activate other immune cells’ functions towards protection against visceral leishmaniasis." (PMID 36678364, 2022). "With this background, the r-LdODC protein as well as its derived HLA-DRB1-restricted synthetic peptides (P1: RLMPSAHAI, P2: LLDQYQIHL, P3: GLYHSFNCI, P4: AVLEVLSAL, and P5: RLPASPAAL) were validated in BALB/c mice against visceral leishmaniasis." (PMID 36678364, 2022).
adenovirus infection (1 paper, 2025). "In contrast, 10 (15.6%) of the 64 controls (including 12 adenovirus-infected patients without elevated liver enzyme concentrations and 33 patients with elevated liver enzyme concentrations but without adenovirus infection) had the HLA-DRB1 04:01 genotype." (PMID 40079016, 2025).
Adult onset (1 paper, 2022). Onset of disease manifestations in adulthood, defined here as at the age of 16 years or later. "Analyses of amino acid positions within HLA-DRB1 indicated that the strongest association was at position 37 (omnibus P = 3.3 × 10−19), with suggestive evidence this association was independent of position 74 (omnibus P = 5.1 × 10−5), the position most strongly associated with adult-onset DM." (PMID 35094092, 2022).
age (1 paper, 2024). A temporal measurement of the time period elapsed since an identifiable point in the life cycle of an organism. "Conversely, other HLAs, such as HLA-A1*01, HLA-DRB1∗13:02 HLA-DRB1*04:04 or HLA-DRB1*04:01, protect against age-related cognitive deterioration." (PMID 39126112, 2024).
American cutaneous leishmaniasis (1 paper, 2013). "The present study sought to investigate the association between HLA-A, HLA-B and HLA-DRB1 genes and susceptibility or resistance to the different clinical manifestations of American cutaneous leishmaniasis (ACL) in southern Brazil." (PMID 23638805, 2013).
amyotrophic lateral sclerosis (1 paper, 2018). Amyotrophic lateral sclerosis (ALS) is a neurodegenerative disease characterized by progressive muscular paralysis reflecting degeneration of motor neurons in the primary motor cortex, corticospinal tracts, brainstem and spinal cord. "Further, investigating the functional links within the C6orf10/LOC101929163/HLA-DRB1 pathway will be critical to better define age-dependent pathogenesis of frontotemporal dementia and amyotrophic lateral sclerosis." (PMID 30252044, 2018).
attention deficit-hyperactivity disorder (1 paper, 2019). A disorder characterized by a marked pattern of inattention and/or hyperactivity-impulsivity that is inconsistent with developmental level and clearly interferes with functioning in at least two settings (e.g. at home and at school). "Specifically, the A2 allele of HLA-A, several HLA-B alleles, as well as HLA-DRB1 DR4 have been reported to be associated with ASD, the latter also being associated with attention deficit hyperactivity disorder (ADHD)." (PMID 30976114, 2019).
autoimmune PAP (1 paper, 2023). "They conducted a genome-wide association study in patients of Japanese ancestry and demonstrated an association of the HLA-DRB1*08:03 allele with a risk of autoimmune PAP and high levels of anti-GM-CSF auto-Abs." (PMID 36821021, 2023).
borderline leprosy (1 paper, 2009). A form of leprosy in which there are clinical manifestations of both principal types (lepromatous and tuberculoid). "Therefore, HLA-DRB1*1601 was associated with susceptibility to Borderline leprosy." (PMID 19698125, 2009).
bronchiolitis (1 paper, 2019). Inflammation of the bronchioles characterized by swelling of the bronchioles and mucus accumulation. "No variants overlap between phenotypes, but there is some overlap at the gene level, namely, HLA-DRB1 in both OM and pneumonia and MUC6 in both bronchiolitis and pneumonia." (PMID 32010199, 2019).
cerebral malaria (1 paper, 2008). A sequestration of Plasmodium falciparum in the brain, which can cause coma and/or seizures. "This allele was not in significant LD with HLA-DRB1 and HLA-B alleles indicating that association with susceptibility to cerebral malaria was not because of LD with the HLA alleles." (PMID 18194515, 2008).
chronic hepatitis (1 paper, 2024). An active inflammatory process affecting the liver for more than six months. "For example, Chinese patients exhibit heightened hepatitis risk with HLA B*48 and DRB1*48 genotypes, whereas acute hepatitis B patients in the same population have lower occurrences of HLA-DRB1*11:01/11:04 and HLA-DQA1*03:01 compared to those with chronic hepatitis." (PMID 38392185, 2024).
co-infection (1 paper, 2011). "HIV co-infection and the number of HLA-DRB1*0701 alleles were also significantly associated with QFT-IT indeterminate results (OR = 99.59 [95% CI, 15.85–625.61] and 4.25 [95% CI, 1.27–14.16] respectively)." (PMID 21886824, 2011). "When non-positive (negative and indeterminate) results of QFT-IT were compared with positive results, increased age by year, BMI <16.0, HIV co-infection and the number of HLA-DRB1*0701 alleles showed similarly high odds ratios." (PMID 21886824, 2011). "Age increased by year, body mass index <16.0, HIV co-infection and the increased number of HLA-DRB1*0701 allele that patients bear showed significant associations with IGRA negativity (OR = 1.04 [95% CI, 1.01–1.07], 5.42 [1.48–19.79], 6.38 [1.78–22.92] and 5.09 [2.31–11.22], respectively)." (PMID 21886824, 2011). "In the final model, increased age by year, BMI <16.0, HIV co-infection and the number of HLA-DRB1*0701 alleles showed significant association with QFT-IT negativity (OR = 1.04 [95% CI, 1.01–1.07], 5.42 [95% CI, 1.48–19.79], 6.38 [95% CI, 1.78–22.92] and 5.09 [95% CI, 2.31–11.22] respectively)." (PMID 21886824, 2011). "With QFT-IT indeterminate results, HIV co-infection, low lymphocyte count, MDR and the number of HLA-DRB1*0701 alleles showed significant associations (OR = 64.74 [95% CI, 17.23–243.20], 26.19 [95% CI, 8.00–85.72], 6.37 [95% CI, 1.64–24.68] and 4.66 [95% CI, 1.83–11.88], respectively)." (PMID 21886824, 2011).
colorectal adenoma (1 paper, 2018). An adenoma that arises from the colon or rectum. "Furthermore, HLA-DRB1 is differentially expressed in precancerous colorectal adenomas mucosa." (PMID 30186855, 2018).
common variable immunodeficiency (1 paper, 2024). "In addition, susceptibility to common variable immunodeficiency (CVID) and deficiency of IgA (sIgAD), both IEI, has also been found to be positively associated with HLA-DQ and HLA-DRB1 alleles." (PMID 39835139, 2024).
Cryptosporidium infection (1 paper, 2021). "Moreover, we previously identified associations between alleles HLA-B*15, HLA-DQB1*03:01 and haplotype HLA-DRB1*11:01/HLA-DQB1*03:01 with increased incidence of asymptomatic and symptomatic Cryptosporidium infection." (PMID 33910121, 2021).
cutaneous sarcoidosis (1 paper, 2024). "Other researchers have shown that the HLA-DRB1*0302 gene is associated with the risk of cutaneous sarcoidosis." (PMID 39598118, 2024).
diabetic foot ulcers (1 paper, 2025). "We investigated the role and mechanism of hsa-HLA-DRB1 in the development and progression of diabetic foot ulcers." (PMID 40419622, 2025). "This study provides strong evidence suggesting that hsa-HLA-DRB1 and other circRNAs may play significant functional roles in the development of diabetic foot ulcers." (PMID 40419622, 2025). "Compared to normal tissue, hsa-HLA-DRB1 was highly expressed in diabetic foot ulcers." (PMID 40419622, 2025). "Of note, the hsa-HLA-DRB1/miRNA_12118/FLT-1 axis was identified, which may have a crucial role in the development of diabetic foot ulcers." (PMID 40419622, 2025).
diabetic retinopathy (1 paper, 2021). "The present study and other studies in diabetic retinopathy demonstrated the HLA-DRB1*03 and HLA-DRB1*04 alleles as the most prevalent." (PMID 34362434, 2021).
diverticular disease (1 paper, 2024). A complex disorder characterised by mucosal outpouchings (diverticulae) of the colonic wall which can become infected and inflamed leading to diverticulitis, perforation and bleeding. "Two GWS genes (EHMT2 and HLA-DRB1) overlapped between T2D, IBD, and diverticular disease." (PMID 38802514, 2024).
enthesitis (1 paper, 2025). Inflammation at the site of insertion of ligaments, tendons, and other fibrous structures into bone. "For instance, the HLA-DRB1*01 haplotype is positively associated with oligoarticular JIA, whereas oligoarticular and poliarticular JIA share a strong association with the HLA-DRB1*08 haplotype, and enthesitis-related JIA is associated with the HLAB27 haplotype." (PMID 40408229, 2025).
eumycetoma (1 paper, 2020). "Interestingly, the HLA-DRB1*02 allele had a high frequency in the control group (9.8%, P = 0.047) whilst it was absent in the eumycetoma patients, suggesting a protective role against eumycetoma." (PMID 32352976, 2020). "Based on this, Al Dawi and colleagues analysed HLA-DRB1 and HLA-DQB1 allele frequencies amongst confirmed eumycetoma patients compared with matched controls." (PMID 32352976, 2020).
fungal infections (1 paper, 2025). "The association between the HLA-DRB1*1501 allele and fungal infections has been widely discussed in the literature, and our findings further support its role in shaping both mycobiota composition and MS progression." (PMID 40791596, 2025).
gastric ulcer (1 paper, 2016). An ulcerated lesion in the mucosal surface of the stomach. "A negative association with HLA-DRB1*1501 allele, reported in H. pylori-positive patients with gastric ulcers when compared with uninfected healthy controls, further supported this potential protective role mediated by HLA-DRB1*1501 restricted HpaA88-100 specific CD4+ T cell response." (PMID 27509059, 2016).
glaucoma (1 paper, 2021). Increased pressure in the eyeball due to obstruction of the outflow of aqueous humor. "Studies have suggested that the autoimmune system could have a role in the development of glaucoma: a higher frequency of the HLA-DRB1*0407 haplotype was reported in Mexican POAG patients compared to controls." (PMID 34348663, 2021).
H1N1 influenza (1 paper, 2016). "Initially, we were interested in identifying 9-11mer epitopes from conserved proteins (M1, M2, NS1, PB1, PB2, PA and NP proteins) derived from the H1N1 influenza strain A/Puerto Rico/8/34 capable of binding to both HLA-A*02:01 and HLA-DRB1*01:01." (PMID 26731261, 2016).
hemochromatosis (1 paper, 2025). A disorder of iron metabolism characterized by a triad of HEMOSIDEROSIS; LIVER CIRRHOSIS; and DIABETES MELLITUS. "We note that the high number of hemochromatosis variant carriers in this cohort can be attributed to linkage disequilibrium between HFE Cys282Tyr and the HLA-DRB1*15:01 MS risk allele." (PMID 41372986, 2025).
hypersensitivity pneumonitis (1 paper, 2022). Hypersensitivity pneumonitis (HP) is a pulmonary disease with symptoms of dyspnea and cough resulting from the inhalation of an antigen to which the subject has been previously sensitized. "Similarly, HLA-DRB1*04 and some alleles of the ancestral haplotype (HLA-DRB1*03:01-DQB1*02:01) are associated with hypersensitivity pneumonitis (HP)." (PMID 36359012, 2022). "Thus, for example, the allele HLA-DRB1*03:01 was found remarkably increased in a subset of patients with hypersensitivity pneumonitis with the presence of circulating autoantibodies, which is also associated with a higher mortality." (PMID 36359012, 2022).
hypoparathyroidism (1 paper, 2025). Hypoparathyroidism is an endocrine disorder in which the parathyroid glands in the neck do not produce enough parathyroid hormone (PTH). "Furthermore, HLA associations support an adaptive immune contribution: HLA-A*26:01 (MHC class I) is strongly linked to idiopathic hypoparathyroidism, implicating CD8+ cytotoxic T-cells, while HLA-DRB1*01 and HLA-DRB1*09 alleles are enriched in affected patients." (PMID 41465179, 2025).
idiopathic membranous nephropathy (1 paper, 2018). "The associations of single nucleotide polymorphisms (SNPs) in PLA2R1 and HLA-DQA1, as well as HLA-DRB1*15:01-DQB1*06:02 haplotype with idiopathic membranous nephropathy (IMN) is well known." (PMID 30349113, 2018).
Insulin resistance (1 paper, 2021). Increased resistance towards insulin, that is, diminished effectiveness of insulin in reducing blood glucose levels. "Moreover, in obese adolescents, the development of insulin resistance was associated with a down-regulation of HLA-DRB1." (PMID 34638758, 2021).
joint diseases (1 paper, 2022). "It plays a great role in the progress of bone and joint diseases including OA and KBD Precisely, it has been reported that HLA-DRB1 is related to the susceptibility of OA." (PMID 35038982, 2022).
Large vessel vasculitis (1 paper, 2015). A type of vasculitis (inflammation of blood vessel walls) affecting large arteries such as the aorta and branches of the aorta. "Of interest, in Japan (where HLA-DRB1*04 population frequency is low), large-vessel vasculitis (Takayasu arteritis) is relatively more common than GCA." (PMID 26223536, 2015).
leukemia (1 paper, 2025). A malignant (clonal) hematologic disorder, involving hematopoietic stem cells and characterized by the presence of primitive or atypical myeloid or lymphoid cells in the bone marrow and the blood. "The data indicate a statistically significant correlation between these HLA alleles and various forms of leukemia in Moroccan patients, suggesting that HLA-B*44, HLA-DRB1*01, and HLA-DRB1*13 may either predispose persons to or confer protection against leukemia." (PMID 40508101, 2025).
Liver abscess (1 paper, 2018). A circumscribed area of pus or necrotic debris in the liver. "Thus, the role of HLA-DRB1 alleles is considered as a genetic predisposing factor to infection with Entamoeba histolytica like in this study, complications of this disease similar to liver abscess and potential predictor response to treatment as pharmacogenetic marker." (PMID 30416723, 2018).
lumbar disc herniation (1 paper, 2021). "In other work, the HLA-DRB1 genotype increased the risk of developing pain after surgery or lumbar disc herniation." (PMID 34020649, 2021).
lymphocytic hypophysitis (1 paper, 2023). "Additionally, he had HLA-DR15 encoded by HLA-DRB1*15:01, which is associated with ICI-related IAD, and DR53 encoded by DRB4, which is associated with lymphocytic hypophysitis." (PMID 38035072, 2023).
measles (1 paper, 2022). A highly contagious viral infection caused by the measles virus. "For example, HLA-DRB1*03, HLA-DPA1*0201, and HLA-DRB*0701 are associated with poor immune responses in measles and hepatitis B vaccines, respectively." (PMID 35632439, 2022).
megacolon (1 paper, 2012). "The frequencies of HLA-DRB1*01 and HLA-B*14:02 were significantly lower in patients suffering from megacolon as well as in those with ECG alteration and/or megacolon compared with a group of patients with indeterminate symptoms." (PMID 22448298, 2012).
Meniere disease (1 paper, 2016). A disease of the inner ear (labyrinth) that is characterized by fluctuating sensorineural hearing loss; tinnitus; episodic vertigo; and aural fullness. "Some studies have found an association between HLA-DRB1 alleles and Meniere’s disease." (PMID 27602337, 2016).
mixed cellularity Hodgkin lymphoma (1 paper, 2017). "Additionally, independent loci within the HLA region are observed for nodular sclerosis Hodgkin lymphoma (rs9269081, HLA-DPB1*03:01, Val86 in HLA-DRB1) and mixed cellularity Hodgkin lymphoma (rs1633096, rs13196329, Val86 in HLA-DRB1)." (PMID 29196614, 2017).
mucositis (1 paper, 2017). Mucositis is inflammation and damage of the mucous membranes lining the mouth and other parts of the gastrointestinal (GI) tract. "Furthermore, we identified a specific isoform of the immunomodulatory gene, HLA-DRB1, which may serve as a biomarker for mucositis severity." (PMID 28052121, 2017). "Furthermore, our results suggested that the expression levels of HLA-DRB1 and HLA-DRB5 may serve as potential predictive biomarkers for mucositis severity." (PMID 28052121, 2017).
mumps (1 paper, 2019). "All four mumps patients expressing an HLA-DRB1*04 molecule showed a good CD4+ T cell response against the GTYR peptide, including the mumps case from which the clone was derived from (HLADRB1*04/1501)." (PMID 30626672, 2019). "Next, the clinical relevance was investigated by evaluating GTYR peptide T cell responses in mumps cases with HLA-DRB1*04 type and in mumps cases with alternative HLA-DRB1 types." (PMID 30626672, 2019). "Significant T cell responses could also be induced in PBMCs from mumps cases with other HLA-DRB1 genotypes." (PMID 30626672, 2019). "Moreover, the epitope was predicted to bind a broad variety of common HLA-DRB1 alleles, which was confirmed by the epitope-specific cytotoxic/Th1 CD4+ T cell responses observed in multiple mumps cases with various HLA-DRB1 genotypes." (PMID 30626672, 2019).
myelitis (1 paper, 2021). An inflammatory process affecting the spinal cord. "Two of the 3 patients who developed myelitis associated to CHIKV infection carry the HLA-DRB1*03:01 allele, linked to NMOSD in Brazilian patients from Rio de Janeiro, whereas that same allele was identified in only one individual without neurological manifestations." (PMID 33815474, 2021).
myelodysplastic syndrome (1 paper, 2022). A clonal hematopoietic disorder characterized by dysplasia and ineffective hematopoiesis in one or more of the hematopoietic cell lines. "Notably, HLA-DRB1*08:02:01G was significantly associated with myelodysplastic syndrome." (PMID 35626230, 2022).
myeloid leukemia (1 paper, 2024). A clonal proliferation of myeloid cells and their precursors in the bone marrow, peripheral blood, and spleen. "Unfortunately, the literature regarding the role of HLA-DRB1*15:01:01 in CLL occurrence is not sufficiently extended and only mentions the involvement of this allele in myeloid leukemias." (PMID 39329950, 2024).
Myelopathy (1 paper, 2023). Myelopathy is an descriptive term, referring to pathology leading to a neurologic deficit related to the spinal cord. "In addition, a GWAS of HTLV-1-associated myelopathy/tropical spastic paraparesis (HAM/TSP) patients and asymptomatic HTLV-1 carriers identified HLA-DRB1*15:01 (reported P = 1.06 × 10−5, OR = 0.59) and HLA-DQB1*06:02 (reported P = 1.78 × 10−6, OR = 0.43) as top protective alleles." (PMID 37903429, 2023).